SIX1 (SIX homeobox 1)
Diseases named in the same sentence as SIX1 in open-access papers (continued):
Sharing a sentence is not in itself a finding about the gene and the disease.
pancreatic ductal adenocarcinoma (2 papers, 2013 to 2017). An infiltrating adenocarcinoma that arises from the epithelial cells of the pancreas. "The gene expression pattern of Six1 in pancreatic ductal adenocarcinomas was compared with their clinicopathological characteristics." (PMID 23527134, 2013). "About 67% (18 of 27) of advanced stage (III & IV) of pancreatic ductal adenocarcinomas were found to overexpress Six1." (PMID 23527134, 2013). "The expression of Six1 mRNA in pancreatic ductal adenocarcinomas samples was significantly higher than in the adjacent non-tumor pancreatic tissues after normalization using GAPDH (P<0.01)." (PMID 23527134, 2013).
prostate tumor (2 papers, 2015 to 2023). "In the study, we investigated the expression patterns of Six1, by Western blotting using fresh prostate tissues, and by IHC using TMA containing a large cohort of prostate tumor samples (144 cases) with complete clinicopathological and follow-up data." (PMID 26161040, 2015).
renal dysplasia (2 papers, 2022 to 2024). Renal dysplasia is a form of renal malformation in which the kidney(s) are present but their development is abnormal and incomplete. "In LER (CD−M2), Ush1c, Otogl, Gjb2, and Eps8 were associated with NSHL; Ush1c and Clrn1 with Usher syndrome, Six1 with branchiootorenal syndrome; Gjb2 with skin phenotype and HL; Gata3 with hypoparathyroidism, sensorineural hearing loss, and renal dysplasia; and Col9a2 with Stickler syndrome." (PMID 39684410, 2024).
Alzheimer disease (1 paper, 2024). A progressive, neurodegenerative disease characterized by loss of function and death of nerve cells in several areas of the brain leading to loss of cognitive function such as memory and language. "For Alzheimer’s disease, the single differentially methylated IGR bb-CpG (cg03032497) in blood samples was mapped in an enhancer region between the SALRNA1 and SIX1 genes." (PMID 39060467, 2024).
Anxiety (1 paper, 2021). Intense feelings of nervousness, tension, or panic often arise in response to interpersonal stresses. "The transcription factor SIX1 was annotated to a cluster of over-expressed genes in high-anxiety mice exposed to LPS immune challenge." (PMID 33856433, 2021).
astrocytoma (1 paper, 2023). "Research has shown that the upregulation of cyclin proteins and ERK signaling is promoted by the interaction between overexpressed EYA2 and Six1, which leads to increased proliferation and invasion of astrocytoma cells." (PMID 37156847, 2023).
brain tumor (1 paper, 2019). "In addition, our study shows that SIX1 promotes stem-like or undifferentiated phenotypes in fibroblastic and brain tumor cells, linked to the regulation of the stemness factor Sox2." (PMID 30723235, 2019).
colon adenocarcinoma (1 paper, 2021). "To investigate SIX1 expression in the nine CTC lines, we compared the microarray expression data obtained in these lines and in the primary HT-29 and metastatic SW620 colon adenocarcinoma cell lines." (PMID 34771571, 2021).
craniosynostosis (1 paper, 2022). Craniosynostosis is defined as the premature fusion of one or more cranial sutures leading to secondary distortion of skull shape resulting in skull deformities with a variable presentation. "Craniosynostosis is associated with heterozygous SIX1 variants, with possible enrichment of loss-of-function variants compared with classical BOS." (PMID 33436522, 2022). "From 1629 unrelated cases with craniosynostosis we identified seven different SIX1 variants (three missense, including two de novo mutations, and four nonsense, one of which was also present in an affected twin)." (PMID 33436522, 2022). "We investigated probands with craniosynostosis of unknown cause using whole exome/genome (n=628) or RNA (n=386) sequencing, and performed targeted resequencing of SIX1 in 615 additional patients." (PMID 33436522, 2022). "We recommend screening of SIX1 in craniosynostosis, particularly when sagittal±lambdoid synostosis and/or any BOS phenotypes are present." (PMID 33436522, 2022).
diffuse large B-cell lymphoma (1 paper, 2015). "The approach to inhibit oncogenic protein-protein interactions by particular peptides or small molecules has been realized for BCL6 in diffuse large B-cell lymphoma and may be applicable to SIX1 as well, disturbing its oncogenic transcriptional activity." (PMID 26473286, 2015).
epilepsy (1 paper, 2021). A brain disorder characterized by episodes of abnormally increased neuronal discharge resulting in transient episodes of sensory or motor neurological dysfunction, or psychic dysfunction. "Interestingly, we observed that when compared to the normal controls, the expression of some identified genes was only significantly altered either in Epilepsy (EGLN1, ELAVL4, and NFE2l2) or Hemorrhage (USP22, EYA1, SIX1, OAS3, SRMS) groups." (PMID 34588521, 2021).
Esotropia (1 paper, 2021). A form of strabismus with one or both eyes turned inward ('crossed') to a relatively severe degree, usually defined as 10 diopters or more. "Such a mechanism would explain the low expression of MYOD in the lateral rectus muscle of the paralytic esotropia group, while SIX1, PAX7 and MYOG are up-regulated." (PMID 34044792, 2021). "The results of RT-PCR revealed that PAX7, MYOG, PITX1, SIX1 and SIX4 showed higher levels of expression, while that of MYOD a lower level of expression within the paralytic esotropia group as compared with that in the control group (p < 0.05)." (PMID 34044792, 2021).
head and neck carcinoma (1 paper, 2023). A carcinoma that arises from the head and neck region. "In this figure, SIX1 represents the SIX family, and there were no data regarding PAX2 and SALL1 in head and neck carcinoma according to the TCGA database." (PMID 36983712, 2023).
heart failure (1 paper, 2016). Inability of the heart to pump blood at an adequate rate to meet tissue metabolic requirements. "Several have been shown to be adversely associated with heart failure, namely the transcription factors HOP homeobox (Hopx) and Six homeobox 1 (Six1), the cytoskeletal regulator tropomodulin 4 (Tmod4), and the metabolic gene nicotinamide riboside kinase 2 (Nmrk2)." (PMID 27469509, 2016).
lactic acidosis (1 paper, 2025). Metabolic acidosis characterized by the accumulation of lactate in the body. "In addition, lactic acidosis caused by the SIX1/LDHA axis contributes to NK cell dysfunction in pancreatic cancer." (PMID 40165895, 2025). "Lactic acidosis induced by the SIX1/LDHA axis in cancer cells also leads to NK cell dysfunction." (PMID 40165895, 2025).
lipodystrophy (1 paper, 2024). A congenital or acquired disorder characterized by abnormal loss or redistribution of the adipose tissue in the body. "Using two novel transgenic mouse models, we found evidence for a role for Six1 in lipodystrophy and fibrotic features observed in the SQ bleo model." (PMID 38826482, 2024).
liver diseases (1 paper, 2024). "Exogenous molecules, such as curcumin, acetaminophen, and corosolic acid, and endogenous molecules, such as microRNAs, UAP1L1, and SIX1, affect certain liver diseases through the O-GlcNAc metabolic pathway." (PMID 38786029, 2024).
malignant phyllodes tumor (1 paper, 2023). A phyllodes tumor with sarcomatous stroma. "PAX3 and SIX1 immunohistochemistry and gene expression have recently been identified in borderline and malignant phyllodes tumors and correlated with poor clinical outcomes." (PMID 37568749, 2023).
meningioma (1 paper, 2023). A generally slow growing tumor attached to the dura mater. "SIX1 and EYA2 functioned together to support the expression of leptin receptors, which promoted the proliferation of meningioma patient-derived cell lines." (PMID 36750914, 2023).
mesenchymal tumors (1 paper, 2019). "To evaluate if the differentiation phenotype linked to SIX1 in our experimental tumors could also be observed in human mesenchymal tumors, we interrogated gene expression data from soft tissue sarcomas included in the TCGA database." (PMID 30723235, 2019).
muscle cancer (1 paper, 2024). A malignant neoplasm affecting the skeletal or smooth muscles. "In addition to SIX1, previous works dealing with the effects of myogenic regulatory factors on muscle cancer have discovered their capacity to stimulate cancer cell differentiation and deregulation of the cell cycle leading to tumor growth regression." (PMID 39009887, 2024).
nasopharyngeal carcinoma (1 paper, 2025). A carcinoma arising from the nasopharyngeal epithelium. "Recent research has indicated that ITCH mediates SIX1 ubiquitination and influences the development of nasopharyngeal carcinoma via the CDC27-cyclin B1 signaling pathway." (PMID 40170095, 2025).
neuroblastoma (1 paper, 2015). Neuroblastoma (NB) is the most common solid, extracranial childhood tumor. "SIX1, a transcription factor, is mutated in SH-SY5Y neuroblastoma cells and also detected in the neuroblastoma genomic landscape study." (PMID 25944692, 2015).
non-compaction cardiomyopathy (1 paper, 2018). Left ventricular non-compaction (LVNC) is characterized by prominent left ventricular trabeculae and deep inter-trabecular recesses. "Our data suggest that Six1 may be a good marker for pathological forms of excessive trabeculation in non-compaction cardiomyopathy." (PMID 29979676, 2018).
oral squamous cell carcinoma (1 paper, 2020). "It was also demonstrated that miR‐188 inhibited oral squamous cell carcinoma by targeting SIX1, offering new insights into the detailed molecular mechanisms of oral squamous cell carcinoma." (PMID 32592428, 2020).
Osteopenia (1 paper, 2025). Osteopenia is a term to define bone density that is not normal but also not as low as osteoporosis. "To further analyze the diversity of MSCs in osteopenia and their potential functional differentiation, we conducted a detailed subtype analysis and identified three MSC subtypes with different molecular characteristics and functional states: C1 SIX1+ MSCs, C2 NR4A1+ MSCs, and C3 KLF4+ MSCs." (PMID 41262236, 2025).
renal hypoplasia (1 paper, 2021). Renal hypoplasia is a developmental anomaly in which one or both kidneys (unilateral or bilateral renal hypoplasia, respectively) have a deficit in the number of nephrons and may be small. "The deletion of SIX1 and the combined deletion of SIX1 and SIX4 resulted in severe renal hypoplasia in mice and pigs." (PMID 34513929, 2021).
retinal degeneration (1 paper, 2016). Degeneration of the retina. "Overexpression of Six1 in the postnatal stage results in destabilized photoreceptor gene expression in the mature retina and causes postnatal onset of retinal degeneration." (PMID 27677711, 2016).
thymic carcinoma (1 paper, 2023). Thymic carcinoma (TC) is a type of thymic epithelial neoplasm characterized by a high malignant potential. "Additionally, we discovered that pan-thymic epithelium markers, exemplified by PAX9 and SIX1, were notably suppressed in thymic carcinomas, suggesting another distinctive feature of this tumor type." (PMID 38201543, 2023). "Additionally, the suppression of general thymic epithelium markers, represented by PAX9 and SIX1, was observed in thymic carcinomas." (PMID 38201543, 2023). "Additionally, the pan-thymic epithelium markers, exemplified by PAX9 and SIX1, were significantly suppressed in thymic carcinomas." (PMID 38201543, 2023). "Therefore, we investigated the correlation between methylation and mRNA expression status in the genes newly identified as activated or suppressed in thymic carcinomas, specifically HIPK2, HDAC9, NFATC1, PAX9, and SIX1 (the methylation status of FEZF2 was not available in the dataset)." (PMID 38201543, 2023).
uterine cancer (1 paper, 2022). Primary or metastatic malignant neoplasm involving the uterine corpus and/or the cervix. "Another study also indicated that the SIX1 oncoprotein correlated with uterine cancer." (PMID 35205261, 2022).
tumor (129 papers, 2006 to 2026). "Ocular sinus homology cassette homolog 1 (SIX1) is closely associated with NK cell dysfunction in tumor tissues." (PMID 40696413, 2025). "SIX1 protein overexpression was associated with TNM (tumor, node, metastasis), poor survival, and venous infiltration in HCC." (PMID 39199296, 2024). "Sine oculis homeobox homolog 1 (SIX1) is a transcription factor associated with aerobic glycolysis during tumor growth." (PMID 36532721, 2022). "As a key transcription factor, SIX1 has been implicated in the glucose metabolism that promotes glycolysis and tumor growth by stimulating glycolytic genes (such as GLUT1, ENO1, and LDHA) transcription." (PMID 32399910, 2021). "The results of loss of function assays showed that the tumor-promoting effect of SIX1 on HCC cell progression is dependent on O-GlcNAcylation." (PMID 32863962, 2020). "To gain further insights into the genetic basis of the tumor phenotype caused by SIX1, we analyzed the global results obtained with RNASeq." (PMID 30723235, 2019). "SIX1 is frequently overexpressed in these tumors and it has been associated to several traits critical for tumor formation and progression, such as proliferation, angiogenesis, invasion and cancer stem cell function." (PMID 30723235, 2019). "Downregulation of the endogenous SIX1 by shRNA in TPC-1 cells not only showed a trend of slowing down the tumor associated weight loss, but also significantly reduced the volume as well as the weight of xenografted tumors." (PMID 31921695, 2019). "Our mouse xenograft model also confirmed that decreased SIX1 abundance was associated with significantly reduced tumor volume and suppression of STAT3 signaling." (PMID 31921695, 2019). "They demonstrated that overexpression of Six1 is associated with tumour stage, lymph node status and grading." (PMID 28388884, 2017). "Among several genes implicated in the regulation of transcription, we found SIX1, coding for a homeobox transcription factor implicated in cell differentiation and tumor progression." (PMID 21853123, 2011). "Mutations in SIX1 and miRNAPGs, as well as gain of chromosome 1q, were also found to be potential drivers of WT progression and relapse by the Children's Oncology Group Renal Tumor Committee (COG‐RTC) (n = 51 relapses (45 paired primary samples))." (PMID 40439002, 2025). "Thus, loss of SIX1, in both zebrafish and mouse xenograft models, results in profound inhibition of tumor growth." (PMID 39902277, 2024). "With WNT5A being one of only seven genes significantly upregulated in SIX1/2-Q177R tumors compared to other blastemal tumors in both expression datasets, it is a strong candidate for promoting tumor progression and the chemotherapeutic resistance associated with SIX1/2-Q177R." (PMID 37815464, 2023). "However, our data mining based on the GSE31210 showed that the high SIX1 expression was associated with advanced tumor stage and a high level of SIX1 was correlated with shortened time to relapse and decreased OS in patients with NSCLC." (PMID 35069900, 2022). "As both MCA205 cells and TC1 cells were derived from C57BL/6N mice, we established syngeneic tumor models using immunocompetent (C57BL/6N) mice transplanted with either WT or Six1−/− tumor cells to visually observe the effects of Six1 deficiency on tumor growth." (PMID 34782761, 2021). "In addition, increased expression of CD8α, CXCL9, CXCL10, Granzyme A (GZMA), Granzyme B (GZMB), and IFN-γ was observed in Six1-deficient tumor tissues." (PMID 34782761, 2021). "However, the role of SIX1 in tumor growth and its associated mechanisms involved in regulating the TME remain to be elucidated." (PMID 34782761, 2021). "To determine whether Six1 deficiency could attenuate tumor growth in an immune-dependent manner, we also established a subcutaneous transplant tumor model with immunodeficient (nude) mice." (PMID 34782761, 2021). "We could show that miR‐155‐3p acts as a promoter of tumours by targeting Six1 and inhibiting Six1‐associated pathways." (PMID 32220051, 2020).
tumor (continued). "The analysis of tumors with SIX1 overexpression indicate that the oncogenic effect of SIX1 is associated with the repression of a senescent gene signature and the induction of a dedifferentiated tumor phenotype mediated, at least in part, by the stemness regulator Sox2." (PMID 30723235, 2019). "Although there was not different expression of SIX1 between Grade II and Grade III of HIV associated AC, the staining of HIV associated SCC with an anti-SIX1 was variable with poorly differentiated tumor tissue (Grade III) showing higher expression of the protein." (PMID 30177858, 2018). "Moreover, elevation of Six1 in human RMS patients is significantly associated with a later tumour stage." (PMID 17008870, 2006). "In addition, the homozygosity of the SIX1-Q177R mutation in the tumor from which the ChIP-seq had been derived as well as the differing treatment regimens between the tumors that had been included in the ChIP-seq and RNA-seq datasets, make for imperfect comparisons." (PMID 37815464, 2023). "All mice bearing WT MCA205 or TC1 cells had developed significant tumor masses at 14 days after transplantation, while none of the mice bearing Six1-deficient MCA205 or TC1 cells had, suggesting that Six1 deficiency could prevent subcutaneous tumor growth in immunocompetent mice." (PMID 34782761, 2021). "Consistent with the transcriptomic findings, immunohistochemistry confirmed higher expression of NOX4, CXCL1, CDKN2A, and SIX1 in CRC tissues than in paired adjacent non-tumor tissues." (PMID 42317343, 2026). "In the cell clusters collected from the lung (C2, C3, C12, C13, and C19), shared TFs among malignant and precancerous cells included LTF, IRX5, SIX1, and RUNX1, associated with tumor invasion and metastasis." (PMID 39872221, 2025). "Eight genes were differentially expressed at both the mRNA and protein levels, with ASCL1, EDNRB, INSM1, SOX11, SOX4, SOX8, and SIX1 showing reduced expression in tumor tissues, and CTNNB1 showing increased expression compared with para-cancer tissues." (PMID 40771813, 2025). "Four primary cell populations were first identified using canonical cell markers: WT tumor cells (WT1, NCAM1, SIX1, SIX2, PAX2), cancer-associated fibroblasts (CAFs) (ACTA2, TAGLN, COL1A1, PDGFRB), endothelial cells (PECAM1, CLDN5, ENG, VWF) and immune cells." (PMID 40098972, 2025). "In RMS, SIX1 preserves the undifferentiating state of tumor cells and SIX1 KD leads to myogenic differentiation and impaired tumor growth." (PMID 39009887, 2024). "In female patients with HCC who were HCV-positive, the upregulation of SIX1 was correlated with tumor growth and poor survival." (PMID 39199296, 2024). "The transcription factor SIX1 directly promotes the expression of key lipogenic genes that facilitate DNL as well as tumor growth and metastasis." (PMID 39258807, 2024). "Our study revealed that LINC02936 promotes tumor progression and suppresses ferroptosis in EC by binding to SIX1 and upregulating CP expression." (PMID 38385087, 2024). "Mechanistically, LINC02936 enhances CP expression by binding to the transcription factor SIX1, which reduces intracellular Fe2+ and ROS levels and suppresses ferroptosis in EC, thus promoting tumor progression." (PMID 38385087, 2024). "Tang and colleagues reported that the lncRNA CRNDE absorbed miR-337-3p and upregulated SIX1, leading to increased tumor progression in HCC." (PMID 39199296, 2024). "In the current study, we identify a phosphor-serine residue (pS225) serving as a molecular switch for the glycolytic and tumor-promoting activities of SIX1." (PMID 39617783, 2024). "More importantly, the level of SIX1 was consistently high in tumor tissue, > 60 years old, G3, dead group, and poor survival, which was consistent with CP in the TCGA-UCEC." (PMID 38385087, 2024). "Here we demonstrate that the SIX1 homeoprotein, which enhances metastasis in most tumor types, suppresses ES metastasis by co-regulating EWS/FLI1 target genes." (PMID 37468459, 2023).